HIF1A (hypoxia inducible factor 1 subunit alpha)
Diseases named in the same sentence as HIF1A in open-access papers (continued):
Sharing a sentence is not in itself a finding about the gene and the disease.
psoriasis (30 papers, 2011 to 2025). An autoimmune condition characterized by red, well-delineated plaques with silvery scales that are usually on the extensor surfaces and scalp. "Secukinumab inhibited both the inflammatory and hypoxic/glycolytic phenotypes associated with psoriasis by modulating the HIF-1α–RHCG axis, thereby disrupting the pathogenic communication between KCs and DCs." (PMID 40351602, 2025). "Most importantly, we discovered that D-mannose, a previously reported inhibitor of HIF-1α and glucose metabolism, had a beneficial effect on psoriasis by restraining the pathogenic γδ17 T cells." (PMID 35296088, 2022). "Excessive proliferation of keratinocytes in psoriasis causes local environmental hypoxia, leading to increased expression of HIF-1α; microenvironment hypoxia accelerates vascular growth to supply the oxygen required for cell growth, along with the elevated expression of VEGFA during this process." (PMID 28399173, 2017). "Consequently, the regulation of the HIF-1α–RHCG signaling axis by secukinumab represents a pivotal mechanism underlying its beneficial effects in ameliorating the pathophysiological manifestations of psoriasis." (PMID 40351602, 2025). "Hypoxia-induced changes in transcription factors, particularly HIF-1α, play a critical role in psoriasis pathogenesis." (PMID 40351602, 2025). "Together, these observations suggest that the HIF-1α/RHCG axis plays a critical role in the therapeutic effects of secukinumab in psoriasis." (PMID 40351602, 2025). "Through its interaction with METTL14, UCA1 activates both HIF‐1α and NF‐κB signaling pathways, consequently promoting keratinocyte‐mediated inflammatory responses and contributing to psoriasis pathogenesis." (PMID 41316520, 2025). "Upregulated expression of HIF-1α has been detected in the skin and serum of patients with psoriasis and other Th17-mediated inflammatory diseases." (PMID 36961533, 2023). "As keratinocytes in psoriasis patients are known to be an important source of HIF‐1α and contribute to skin angiogenesis, we believe the significance to study the role of keratinocytes, including angiogenesis, in the mechanisms of NPWT." (PMID 36704879, 2023). "Evidence suggests that HIF-1α is relevant in psoriasis since in vitro human keratinocytes and HaCaT cells have a high proliferation rate as well as an aberrant differentiation when HIF-1α is increased." (PMID 35563616, 2022). "It has been proposed that pVHL can act as a negative regulator of the transcriptional factor HIF-1α, which was proven to have a role in the pathogenesis of psoriasis." (PMID 35563616, 2022). "AKT/mTOR signaling participates in the progression of psoriasis and tunes the fate of T cell by HIF-1α-mediated glycolysis." (PMID 35296088, 2022). "Expression of HIF-1α was increased in both skin lesions, and serum from patients with psoriasis as compared to those in controls." (PMID 36761171, 2022). "Studies have found that HIF1A levels in patients with psoriasis were significantly higher than those in normal patients and were positively correlated with microvessel density in skin lesions." (PMID 35265149, 2022). "In conclusion, our results show a reduction in pVHL and an enhancement in HIF-1α expression in psoriatic skin models, which strengthens previous findings in psoriasis patients." (PMID 35563616, 2022). "In psoriasis patients, increased expression of HIF-1α in relation to mRNA and protein levels was reported in lesional skin compared with healthy tissue." (PMID 35563616, 2022). "Western blotting analysis also showed that PSORI-CM02 treatment significantly downregulated the expression levels of VEGFR1, VEGFR2, ANG1, and HIF-1α in mice with IMQ-induced psoriasis." (PMID 33995368, 2021). "The role of HIF1A in mediating the potential therapeutic effects of UVB in psoriasis warrants further study." (PMID 33812333, 2021). "PSORI-CM02 treatment reduced the mRNA expression levels of VEGF and HIF-1α in the skin of mice with IMQ-induced psoriasis." (PMID 33995368, 2021).
psoriasis (continued). "Taken together, we indicated miR-150 regulates human keratinocytes’ proliferation in hypoxic conditions through targeting HIF-1α and VEGFA in psoriasis for the first time, and provide diagnostic markers and a potential novel target for psoriasis treatment." (PMID 28399173, 2017). "Taken together, we indicated miR-150 regulates human keratinocytes’ proliferation in hypoxic conditions through targeting HIF-1α and VEGFA in psoriasis for the first time, and provide diagnostic markers and a novel target for psoriasis treatment." (PMID 28399173, 2017). "These indicated that in psoriasis cells, miR-150 inhibits the cell proliferation induced by hypoxia, as well as the accelerated expression of HIF-1α and VEGFA." (PMID 28399173, 2017). "Among HIF-1α dependent LncRNAs, PRINS (Psoriasis susceptibility-related RNA Gene Induced by Stress) was significantly up regulated in hypoxic conditions and had specific interaction with RANTES as confirmed through reporter assay." (PMID 26725683, 2016). "In this review, we will discuss the interaction of HIF-1α with cytokines and cells of the immunological system involved in the pathogenesis of psoriasis." (PMID 26136626, 2015). "In this review, the role of HIF-1α in the cross talk between the cytokines and cells of the immunological system involved in the pathogenesis of psoriasis is discussed." (PMID 26136626, 2015). "Angiopoietins Ang-1 and Ang-2, and their receptor Tie-2, are involved in the angiogenic process of psoriasis and all are induced by HIF-1α." (PMID 26136626, 2015). "In order to find a new therapeutic method for psoriasis, we detected the translation of HIF-1α gene in psoriatic epidermis by in situ hybridization technique before and after 21 days treatment with capsaicin ointment." (PMID 22389862, 2011). "So, in this study, we examined the effect and mechanism of HIF-1α on the proliferation of epidermis of psoriasis." (PMID 22389862, 2011). "Another study reported that HIF1α aggravates psoriasis by inhibiting BMP6 expression." (PMID 38491188, 2024). "In psoriasis, high serum levels of HIF-1α showed a correlation with overexpression of IL-6." (PMID 36961533, 2023). "D-mannose, as a C-2 epimer of glucose, has been reported to impair glycolysis and suppress the activation of HIF-1α; therefore, we hypothesized that it may also have a beneficial effect in the model of psoriasis." (PMID 35296088, 2022). "Through our findings, we speculated that the decreased AKT/mTOR/HIF-1α signaling and glycolytic ability in γδ T cells may contribute to the suppression of psoriasis achieved by D-mannose." (PMID 35296088, 2022). "HIF-1α-dependent glycolysis is implicated in the pathogenesis of Th17 cells; hence, suppressing the activation of HIF-1α and impeding the correlated glycolysis may offer protection in the mouse model of psoriasis." (PMID 35296088, 2022). "Conversely, we observed the overexpression of HIF-1α in lesional compared with healthy skin; however, to date, it is unknown if pVHL could play a role in the pathophysiology of psoriasis." (PMID 35563616, 2022). "In psoriasis, whether the pVHL/HIF-1α regulatory pathway could play a role in the physiopathology has not been explored." (PMID 35563616, 2022). "To elucidate the mechanism underlying the inhibition of psoriatic features in the mouse model caused by the retrieval of pVHL, we determined the expression of pVHL in lesional skin from imiquimod-induced psoriasis-like mice, as well as the expression of its target molecule HIF-1α." (PMID 35563616, 2022).
psoriasis (continued). "This amelioration of the lesions induced by pVHL could be explained by negative regulation of the important molecules in psoriasis, such as HIF-1α, VEGF, LDH and TNF-α." (PMID 35563616, 2022). "In addition, HIF-1α is involved in the differentiation of T helper cell 17 (Th17), a key cellular component in the immunopathogenesis of psoriasis, and in the production of IL-1731." (PMID 34285267, 2021). "Moreover, increased HIF1A expression localises to the keratinocytes adjacent to the inflamed and elongated papillae in psoriasis." (PMID 33812333, 2021). "The effects of hypoxia with elevated levels of HIF-1α and VEGF may explain the association between OSA and psoriasis." (PMID 32246124, 2020). "In addition, HIF-1α is involved in T-cell regulation and survival which are crucial in psoriasis formation." (PMID 32246124, 2020). "It is speculated that cannabinoids have a potential role in treatment of psoriasis by controlling angiogenesis and inflammation through decreasing HIF-1α and VEGF levels." (PMID 31178954, 2019). "By upregulating the expression of cell adhesion molecules, VEGF could enhance the migration of leukocytes into the psoriatic skin and increase oxygen consumption, further activating HIF-1α and perpetuating the angiogenic/inflammatory cycle of psoriasis." (PMID 31178954, 2019). "We suggest that these molecules could be used to control the psoriasis pathology as they act over HIF-1α to control IL-17 production and angiogenesis development." (PMID 26136626, 2015). "Our results suggest that downregulation of HIF-1α mRNA by capsaicin may induce the proliferation and cytokine production of keratinocytes; this may be involved in the pathogenesis of psoriasis." (PMID 22389862, 2011). "Today, only a few studies have experimentally investigated the influence of HIF-1α on psoriasis." (PMID 22389862, 2011). "HIF-1α have high expression in psoriasis and might play an important role in the genesis and development of psoriasis." (PMID 22389862, 2011). "Suppressing HIF-1α-dependent glycolysis could impede the development of Th17 cells and delay the progression of experimental autoimmune encephalomyelitis; therefore, we speculate that manipulation of HIF-1α and glycolysis may also be a potent way to relieve the psoriasis induced by γδ17 T cells." (PMID 35296088, 2022). "Thus, the VEGF pathway may be a crucial link between OS and angiogenesis in psoriasis, especially for the HIF-1α/VEGF signaling pathway playing a synergistic role in the neovascularization of psoriasis." (PMID 31178954, 2019). "In psoriasis, METTL14 interacts with UCA1 to regulate the HIF‐1α/NF‐κB axis, while also modulating the SOCS3/STAT3 pathway to attenuate IL‐6‐mediated inflammation." (PMID 41316520, 2025). "Taken together, this work indicates that UCA1 positively regulates keratinocyte-driven inflammation and psoriasis development by binding to METTL14, and activating HIF-1α and NF-κB signaling pathway." (PMID 37076497, 2023). "Our findings suggest that lncRNA UCA1 promotes keratinocyte-driven inflammation in psoriasis by targeting and inhibiting METTL14 protein and then activating the HIF-1α/STAT3 and NF-κB signaling pathways." (PMID 37076497, 2023). "HIF-1α inhibited expression of BMP6 by binding to the HRE of promoter of BMP6, thereby aggravating the pathological features in psoriasis." (PMID 36761171, 2022). "HIF-1α, VEGF, and VEGFR play crucial roles in the onset and progression of psoriasis and are, therefore, promising targets for the treatment of psoriasis." (PMID 33995368, 2021). "In our study, PSORI-CM02 suppressed the expression of angiogenic mediators, including VEGF, HIF-1α, VEGFR1, VEGFR2, and ANG1, in IL-17A-stimulated HUVECs and in mice with IMQ-induced psoriasis." (PMID 33995368, 2021). "HIF-1α promotes the expression of VEGF, while ANG1 and VEGFR play essential roles in angiogenesis in psoriasis." (PMID 33995368, 2021).
psoriasis (continued). "Besides, miR-150 regulates HIF-1α and VEGFA by direct binding to the 3’UTR of HIF-1α and VEGFA to inhibit human keratinocytes’ proliferation, suggesting that miR-150, HIF-1α and VEGFA may serve as useful diagnostic markers and novel targets for treatment strategies of psoriasis." (PMID 28399173, 2017). "Results from qPCR assays showed that both HIF-1α and VEGFA mRNA was up-regulated in psoriasis tissues." (PMID 28399173, 2017). "Taken together, we demonstrate that the expression of miR-150 is significantly down-regulated in lesional psoriatic skin, and is specifically related to HIF-1α and VEGFA during the psoriasis process." (PMID 28399173, 2017). "Our results showed a positive correlation between RHCG expression, HIF-1α, and glycolysis-related genes, suggesting that RHCG may be regulated through hypoxia-related pathways in psoriasis." (PMID 40351602, 2025). "Notably, HIF1A, IL-6, TNF, and IFNG were co-modulated by more than four BPs, indicating their central role in the mechanism of action of SHTLS in psoriasis treatment." (PMID 40507893, 2025). "The TNF-α, MAPK, HIF-1α, and IL-17 signaling pathways were highly involved in the PPI network of 36 key targets of SHTLS, which are commonly recognized as major pathological features in the development of psoriasis." (PMID 40507893, 2025). "Furthermore, HIF-1α bound to miR-210, suppressed expression of target genes STAT6 and LYN, leading to Th17 cells differentiation in psoriasis mice." (PMID 36761171, 2022). "Most importantly, we determined that D-mannose, a hexose sugar, could alleviate the experimental psoriasis by suppressing γδ T cells via inhibition of glycolysis and AKT/mTOR/HIF-1α signaling." (PMID 35296088, 2022). "These inspired us to presume that miR-150 might regulate HIF-1α and VEGFA to modulate human keratinocytes proliferation in psoriasis." (PMID 28399173, 2017). "Perhaps in the psoriasis Treg cells treated with trichostatin-A occurred that when HDAC-1 was inhibited, the expression of VHL augmented, HIF-1α was proteolyzed, and the expression of IL-17 decreased, giving as result that Treg cells could not switch to Th17." (PMID 26136626, 2015). "Our data collectively indicate that SHTLS exerts multi-level effects on psoriasis pathology—including suppression of keratinocyte hyperproliferation, angiogenesis, and inflammatory cytokine production—through the coordinated regulation of MAPK, NF-κB, and HIF-1α signaling." (PMID 40507893, 2025). "Besides, HIF-1α and VEGFA were reported as crucial regulators during the pathogenesis of psoriasis." (PMID 28399173, 2017). "It has been reported that IL-17A has proangiogenic effects but in a HIF-1α-independent pathway; however, at the same time, IL-17A can stimulate the expression of proangiogenic factors in fibroblast and keratinocytes, including VEGF, feeding back the angiogenesis in psoriasis." (PMID 26136626, 2015). "Therefore, transcriptional activation of HIF‐1α in response to VEGF‐A inhibition in plaques was expected, although this may pinpoint the activation of an early resistance mechanism to anti‐VEGF‐A treatment within plaques of psoriasis." (PMID 39624732, 2024). "HIF-1α and its regulators (HDAC-1, HDAC-7, VHL-E3, PHD2, LL-37, HIF-1β, mTOR, miR-210, RORγt, STAT3, and IL-13Ralpha, as well as glycolysis enzymes) could be important pharmacological targets to restore the lack of regulation in the angiogenesis and in immunological processes involved in psoriasis." (PMID 26136626, 2015).
retinal ischemia (29 papers, 2012 to 2025). A ischemic disease that involves the retina. "HIF1-α is an important regulator of oxygen homeostasis, and is associated with pathological conditions that are caused by hypoxia and retinal ischemia." (PMID 31130920, 2019). "Previously, we demonstrated HIF-1α/BNIP3 pathway could be associated with inner retinal degeneration in a murine model of retinal ischemia/reperfusion injury by a transient induction of high IOP." (PMID 35005021, 2021). "A published study showed that retinal ischemia and hypoxia during DR can induce increased expression of HIF-1α, which promotes the expression of vascular endothelial growth factor (VEGF)." (PMID 36088760, 2022). "Compelling evidence indicates that topotecan administration inhibits HIF-1a expression and improves retinal ganglion cell survival leading to a functional protection against retinal ischemia–reperfusion." (PMID 34465337, 2021). "Administration of halofuginone showed a significant neuroprotective effect by inhibiting HIF-1α expression in a murine retinal ischemia-reperfusion model histologically and functionally." (PMID 31261724, 2019). "When our findings are taken as a whole, XFZYD would seem to have a preventive or protective effect on retinal ischemia via the downregulation of HIF-1α expression and a reduction in VEGF secretion; this ocurrs via an inhibition of RBP2 and PKM2." (PMID 28709426, 2017). "The enhanced mRNA/protein concentrations of RBP2 and PKM2, as well as the consequential stimulation of HIF-1α and VEGF mRNA/protein levels as measured during the present investigation are clearly associated with retinal ischemia and, possibly, wAMD." (PMID 28709426, 2017). "Elevated concentrations of the hypoxia-inducible factor-1α (HIF-1α) have been demonstrated after retinal ischemia." (PMID 28709426, 2017). "Interestingly, we observed that accumulation of HIF-1α in hyperglycemic mice occurs prior to — and independently of — the development of retinal ischemia (or hypoxia)." (PMID 37227777, 2023). "In addition, studies in vivo and vitro have found that PPAR-α agonists had therapeutic effects on ischemic retina diseases, especially on diabetic retinopathy, through the downregulation of HIF-1α in endothelial cells." (PMID 34268320, 2021). "Moreover, PPARα agonists reduced hypoxia-induced HIF-1α expression and activity in cancer cells, and improved ischemic retina diseases through decreasing HIF-1α in endothelial cells." (PMID 34268320, 2021). "Baicalein can also prevent retinal ischemia by reducing the levels of HIF-1α, VEGF, and MMP-9." (PMID 33149752, 2020). "In this aspect, we previously demonstrated that the HIF-1α/BNIP3 pathway could be one of the promising therapeutic targets in retinal degeneration in a murine model of retinal ischemia/reperfusion injury and unilateral common carotid artery occlusion, or a 661W photoreceptor cell line." (PMID 38536853, 2024). "Garlic has also been shown to exert antioxidants and neuroprotective effects, inhibit retinal ischemia, and decrease the expression of VEGF, hypoxia-inducible factor 1 alpha (HIF-1α), inducible nitric oxide synthase (iNOS), and metalloproteinase (MMP)-9." (PMID 35875346, 2022). "Catalpol’s unique action on multiple angiogenic pathways, including β-catenin, HIF-1α, VEGF, and angiopoietin-2, and on inflammatory biomarkers (i.e., MCP-1) suggests that these mechanisms may play key roles in treating retinal ischemia." (PMID 40362263, 2025). "A recent study has shown that SAC was able to protect against retinal ischemia (not an uncommon cause of visual impairment) via inhibiting the upregulation of VEGF, MMP-9, and HIF-1α." (PMID 38279349, 2024). "There is recent evidence from the retinal ischemia rat model that HSPB1 (rather than other common HSPs) is the transcriptional target of the hypoxia-inducible factor (HIF)-1α transcription factor." (PMID 35099007, 2022).
retinal ischemia (continued). "VEGF, a downstream effector of HIF-1α, also showed negative correlations with axial length (p < 0.01), which may indicate a compromised angiogenic response in highly myopic eyes, where VEGF expression is insufficient to counteract choroidal thinning and retinal ischemia." (PMID 41438149, 2025).